ABCA3 (ATP binding cassette subfamily A member 3)
Diseases named in the same sentence as ABCA3 in open-access papers (continued):
Sharing a sentence is not in itself a finding about the gene and the disease.
acute respiratory distress syndrome (2 papers, 2024 to 2025). Progressive and life-threatening pulmonary distress in the absence of an underlying pulmonary condition, usually following major trauma or surgery. "Mutations in ABCA3, such as the autosomal recessive E292V variant, result in severe neonatal acute respiratory distress syndrome (ARDS) or adult-onset interstitial lung disease." (PMID 39768847, 2024).
B-cell lymphoma (2 papers, 2018 to 2022). "Moreover, it has been reported that LCEVs efficiently extrude drugs and can drive drug resistance in aggressive B-cell lymphomas via the ATP-transporter A3-mediated mechanism (ABCA3)." (PMID 30583481, 2018).
cataract - microcornea syndrome (2 papers, 2015 to 2021). Cataract-microcornea syndrome is characterized by the association of congenital cataract and microcornea without any other systemic anomaly or dysmorphism. "Abca3 was expressed in human choroid-retinal pigment epithelium and retinal pigment epithelial cells, mutations in which were associated with cataract-microcornea syndrome (CCMC)." (PMID 26693729, 2015).
childhood interstitial lung disease (2 papers, 2019 to 2021). "Different types of ABCA3 mutations disrupt surfactant synthesis and cause neonatal respiratory failure or childhood interstitial lung disease (chILD) in older infants and children." (PMID 30913273, 2019).
Neonatal respiratory distress (2 papers, 2017 to 2024). Respiratory difficulty as newborn. "Individuals carrying pathological variants of ABCA3 mainly present with either neonatal respiratory distress (NRDS) in full-term infants or chILD in children, or both." (PMID 38226623, 2024).
ovarian carcinoma (2 papers, 2007 to 2021). A malignant neoplasm originating from the surface ovarian epithelium. "ABCA3 was previously identified as an ER-regulated gene, which supports its involvement in breast tumorigenesis, and SPTAN1 was involved in chemotherapy resistance in ovarian cancer, which makes this gene a potential target for cancer treatment." (PMID 17280605, 2007).
pulmonary hypertension (2 papers, 2018 to 2023). Increased pressure within the pulmonary circulation due to lung or heart disorder. "Notably, inhibition of ABCC4 prevents and reverses pulmonary hypertension in mice and ABCA3 deficiency is related to PAH of the newborn." (PMID 29416681, 2018).
viral infection (2 papers, 2011 to 2023). "ABCA3 is a member of the ABC transporter gene family, which could be involved in the mosquito immune response to viral infection." (PMID 37896885, 2023). "However, while many of the ABC genes were found to be differentially expressed in mosquitoes following dengue, yellow fever, and West Nile virus infection, ABCA3 specifically was not identified so its potential antiviral role is unknown." (PMID 37896885, 2023).
asthma (1 paper, 2012). "None of the ABCA3 mutations associated with asthma in the Copenhagen City Heart Study (data not shown)." (PMID 22866751, 2012).
breast tumour (1 paper, 2022). "An early study also indicated that decreased ABCA3 expression is an independent adverse risk factor for breast tumour recurrence (log-rank test p = 0.0053)." (PMID 35631534, 2022). "Nevertheless, the genes ABCA3, ABCA8, ABCA12, ABCC7, and ABCC8 cluster in breast tumours, and the expression of this gene group was associated with the clinical and pathological parameters of tumours." (PMID 35631534, 2022).
bronchopulmonary dysplasia (1 paper, 2025). Bronchopulmonary dysplasia is a chronic respiratory disease that results from complications related to lung injury during the treatment of infant acute respiratory distress syndrome in low-birth-weight premature infants or from abnormal lung development in older infants. "This includes categories labeled as “ILD”, “ILD-Other Cause”, all disorders of surfactant dysfunction (such as SP-B, SP-C, and ABCA3), and bronchopulmonary dysplasia (BPD)." (PMID 40678364, 2025).
colitis (1 paper, 2023). Inflammation of the colon. "Gene expression of the regulatory proteins Abca3 and Ttf1 were also increased and there were trending differences between C57BL/6 and TCRδ-/- mice with colitis." (PMID 37063825, 2023).
colorectal cancer (1 paper, 2024). A primary or metastatic malignant neoplasm that affects the colon or rectum. "ABCA3 expression is associated with poor survival and multidrug resistance in Leukemia cells and may have similar functions in BRAF-mutated colorectal cancer." (PMID 38982444, 2024).
Congenital alveolar capillary dysplasia (1 paper, 2022). "Analyses of genes related to surfactant deficiency and congenital alveolar capillary dysplasia were normal: ATP-binding cassette sub-family A member 3 (ABCA3), surfactant pulmonary-associated protein C and B (SFTPC and SFTPB, respectively) and forkhead box protein F1 (FOXF1)." (PMID 35321730, 2022).
familial infantile myoclonic epilepsy (1 paper, 2019). A rare, genetic, infantile epilepsy syndrome disease characterized by neonatal- to infancy-onset myoclonic focal seizures occurring in various members of a family, associated in some with mild dysarthria, ataxia and borderline-to-moderate intellectual disability. "The deletion region comprises TSC2, PKD1, TBC1D24 and ABCA3 genes and mutations of these genes are associated with tuberous sclerosis complex, autosomal dominant polycystic kidney disease type 1 (ADPKD1) or familial infantile myoclonic epilepsy." (PMID 31060568, 2019).
glioblastoma (1 paper, 2022). The most malignant astrocytic tumor (WHO grade IV). "The lysosome‐associated ABC transporter A3 (ABCA3) regulates exosome biogenesis and ABCA3 depletion enhances the sensitivity of target cells to antibody‐mediated cytotoxicity.[10a] Similarly, bevacizumab is captured by glioblastoma (GBM) cells derived EVs." (PMID 36253096, 2022).
hemangiosarcomas (1 paper, 2014). "ABCA3 expression appeared to be low across a population of cells with high CSF-1R expression enriched from hemangiosarcoma cell lines when expression was examined using microarray anlaysis (J-H." (PMID 25295160, 2014). "Thus ABCA3 may not contribute to lysosomal sequestration in hemangiosarcomas." (PMID 25295160, 2014).
hemochromatosis (1 paper, 2019). A disorder of iron metabolism characterized by a triad of HEMOSIDEROSIS; LIVER CIRRHOSIS; and DIABETES MELLITUS. "In addition, it has been reported that higher expression of ATP binding cassette transporter 3 (ABCA3) and mutation in HFE gene encoding human hemochromatosis protein both independently predicted resistance to the treatment of fractionated GO plus intensive chemotherapy." (PMID 31695916, 2019).
myeloid leukemia (1 paper, 2012). A clonal proliferation of myeloid cells and their precursors in the bone marrow, peripheral blood, and spleen. "Little is known about the expression pattern of the SALL4, ABCA3 and BMI-1 genes in patients with myeloid leukemia and patients that achieved complete remission after chemotherapy." (PMID 23067006, 2012). "The expression level of ABCA3 seemed low in the different myeloid leukemia in comparison with the HI group." (PMID 23067006, 2012). "In order to characterize the expression pattern of SALL4, BMI-1 and ABCA3 genes in patients with myeloid leukemia and those who achieved complete remission (CR) after chemotherapy." (PMID 23067006, 2012).
neuroblastoma (1 paper, 2023). Neuroblastoma (NB) is the most common solid, extracranial childhood tumor. "In the INFORM dataset, only two other transporters (ABCA3 and ABCG4) were significantly (P < 0.05) and relevantly (FC > 2) upregulated in relapsed neuroblastoma compared to other entities." (PMID 36181342, 2023).
osteosarcoma (1 paper, 2021). A usually aggressive malignant bone-forming mesenchymal neoplasm, predominantly affecting adolescents and young adults. "Expression of ABCA3, CTGF, and AMIGO2 were significantly higher in metastatic osteosarcoma samples compared to the primary osteosarcoma samples while the expression of PREB, FHIT, and EXOSC5 were significantly decreased in metastatic osteosarcoma samples." (PMID 34368151, 2021).
prostate tumor (1 paper, 2021). "Using one probe, XLB, here we identified ATP-binding cassette (ABC) transporters ABCA3, ABCB4, and ABCB10 as unfractionated microsomal GlcCer-binding proteins in DU-145 prostate tumor cells." (PMID 34597626, 2021).
respiratory infections (1 paper, 2014). "Onset and progression of ABCA3-related ILDs might be influenced by external stress factors such as respiratory infections." (PMID 24730976, 2014).
Respiratory insufficiency (1 paper, 2025). "The following keywords (alone or in combination) were used: chILDs, newborns, interstitial disease, respiratory insufficiency, surfactant, pediatric, ABCA3, genetic, diagnosis, therapy." (PMID 40507465, 2025).
sphingolipidoses (1 paper, 2025). "ABCA3 pumps lipids and cholesterol into lamellar bodies producing characteristic lipid whorls that are morphologically similar to those seen here and in patient and animal models of sphingolipidoses." (PMID 40608809, 2025).
cancer (17 papers, 2007 to 2025). A tumor composed of atypical neoplastic, often pleomorphic cells that invade other tissues. "Indeed, ABCA-3 has been implicated in lysosomal drug sequestration and exosome shedding in cancer, demonstrating ABCA-3's activity as an intracellular transporter protein for other endosomal compartments in the cell apart from lamellar bodies." (PMID 35265641, 2022). "Other studies have shown that some ABC transporters, including ABCA2, ABCA3, ABCB1, and ABCG2, are associated with cancer cell stemness." (PMID 34244494, 2021). "AT2 markers SFTPB and ABCA3 were simultaneously expressed in a large proportion of cancer cells." (PMID 35874770, 2022). "To investigate the grade of cancer cells, we explored alveolar type I (AT1) and alveolar type II (AT2) cells with annotated markers, including PDPN, AGER, ABCA3, and SFTP gene families." (PMID 35874770, 2022).
tumor (13 papers, 2007 to 2025). "Four other ABC transporters showed this pattern, with elevation in the MDR tumor at least two-fold greater than in the control sample, and reduced by metformin (ABCA3, ABCC10, ABCG1, and ABCB3)." (PMID 36077749, 2022). "However, until now, ABCA3 has not been implicated in tumor metastasis." (PMID 34368151, 2021). "Moreover, the expression of putative Stat3 target genes Abca3 and Etv5 significantly decreased in Stattic-treated KPY tumor organoid cells compared to DMSO treatment (Fig. EV2I)." (PMID 39930268, 2025). "In addition, ABCA3 locates on the lysosome and intracellular multivesicular bodies in drug-resistant tumor cells in AML, realizing subcellular drug isolation and endows tumor cells with drug resistance." (PMID 35692747, 2022). "The average expression level of the ABCA3 (p = 0.007), ABCB9 (p = 0.000), ABCC1 (p = 0.000), ABCC4 (p = 0.000), ABCC5 (p = 0.000), and ABCC6 (p = 0.000) genes was statistically significantly higher in patients without tumor cell infiltration in the lymph vessels." (PMID 36674773, 2023).
infection (7 papers, 2016 to 2024). The state of being infected such as from the introduction of a foreign agent such as serum, vaccine, antigenic substance or organism. "Sftpa1, Sftpb, Sftpc, and Abca3 also declined to 50–75% below uninfected control while Sftpd levels were stable for the first 7 days after infection in the lungs of B2−/− mice." (PMID 28779131, 2017). "These are involved in smooth-muscle function (FGFR1, GATA5 and STIM1), tissue organization (ADAMTS10), alveolar and epithelial function (ABCA3 and CLDN18), and inflammation and immune response to infection (CFH, CYTL1, HMCN1, LRBA and STIM1)." (PMID 36914875, 2023).
genetic disorders (5 papers, 2013 to 2025). "Lamellar body size is an important indication of type II cell health since lamellar body size is altered in a number of genetic diseases such as ABCA3 deficiency and HPS." (PMID 23843985, 2013).
respiratory disease (5 papers, 2016 to 2024). "Homozygous or compound heterozygous mutations in the ABCA3 gene can lead to a loss of ABCA-3 function resulting in severe respiratory disease that can be fatal." (PMID 35265641, 2022). "The results here show significant respiratory diseases associated with likely pathologic variants, such as ABCA3:p.Val1399Met, MUC5B:p.Ile4979Thr, MUC5B:p.Gly5580Arg, MUC5B:p.Glu5621*, SCNN1B:p.Arg206Trp, SCNN1B:p.Glu468Lys, and SFTPA1:p.Gly98Ala." (PMID 33526882, 2021). "This mutation changes the intronic sequence, creates a new donor splice site and leads to aberrant ABCA3 proteins and is the cause of our patient’s fatal respiratory disease." (PMID 27670912, 2016). "We report the case of a full-term baby boy with a homozygous intronic ABCA3 mutation as the cause of his fatal respiratory disease." (PMID 27670912, 2016). "E690K and W308R autosomal recessive ABCA3 mutations cause severe respiratory disease in newborns." (PMID 38226623, 2024). "Mutations in ABCA3 can result in severe respiratory disease in infants and children." (PMID 35265641, 2022). "Initial testing for genetic causes of respiratory disease and PAH (including sequencing for FOXF1, SFTPB, SFTPC, ABCA3) was negative." (PMID 36878902, 2023).
autosomal recessive disease (1 paper, 2026). Autosomal recessive form of disease. "Firstly, the present study was based on molecular investigations of index cases, and for autosomal recessive diseases (e.g., ABCA3, MARS1, CSF2RB), most often concerned the first affected individual in the family." (PMID 41041870, 2026).
inflammation (1 paper, 2024). Aberrant reaction of the microcirculation characterized by movement of fluid and leukocytes from the blood into extravascular tissues. "ABCA3 expression occurs in normal fetuses at 26–27 weeks of gestation, even at 23–24 weeks, associated with lung inflammation, and is developmentally regulated." (PMID 39457702, 2024).
ABCA3 also shares sentences with these, for which no sentence is quoted: autoimmune PAP (3 papers); protein deficiency (3); brain tumor (2); fibrosis (2); immunodeficiencies (2); Interstitial pneumonitis (2); metabolic disease (2); Respiratory distress (2); adenocarcinoma (1); adenocarcinoma of the lung (1); brain-lung-thyroid syndrome (1); bronchiectasis (1); cataract (1); connective tissue disease (1); COPA syndrome (1); COVID-19 (1); dengue (1); diffuse large B-cell lymphoma (1); epilepsy (1); Failure to thrive (1); frontotemporal dementia (1); GM2 gangliosidosis (1); hematological diseases (1); Hermansky-Pudlak syndrome (1); lysinuric protein intolerance (1); myositis (1); neuroendocrine cell hyperplasia of infancy (1); Niemann-Pick disease (1); osteoarthritis (1); pulmonary alveolar microlithiasis (1).
A further 6 diseases each share a sentence with ABCA3 in 1 paper.